CUX1 (cut like homeobox 1)
Diseases named in the same sentence as CUX1 in open-access papers (continued):
Sharing a sentence is not in itself a finding about the gene and the disease.
cancer (continued). "In contrast, CUX1 only functions as an auxiliary factor that accelerates repair of oxidative damage, therefore it is not essential in normal human cells suggesting that CUX1 might represent an ideal therapeutic target for cancer treatment." (PMID 33069104, 2021). "We also noted seven genes marked with “caution” in PeCanPIE showing the truncation close to the C-terminal (CUX1, FLCN, FLG, MSH6, NSD1, PRDM9, and USP6), questioning its functional effects in the cancer context." (PMID 35406420, 2022). "A high-throughput RNAi screening demonstrated that Cux1 knockdown led to impaired cell migration and invasion in NIH-3T3 and a series of human cancer cell lines." (PMID 32547943, 2020). "We show that elevated expression of either CUX1 or OGG1 prevents RAS-induced senescence in primary cells, and that CUX1 knockdown is synthetic lethal with oncogenic RAS in human cancer cells." (PMID 24618719, 2014). "Conversely, knockdown of CUX1 is synthetic lethal for RAS-transformed cells, thereby revealing a potential Achilles' heel of these cancer cells." (PMID 24618719, 2014). "A few genes on chromosome 7 that may play a crucial role in the disease pathogenesis and phenotype of cancers are EZH2, KMT2A, SAMD9, SAMD9L, and CUX1." (PMID 39463522, 2024). "Notably, in the context of cancer, the expression and functions of SATB1/2 and CUX1 have been extensively investigated in numerous studies." (PMID 37744879, 2023). "While the DNA repair function of CUT domain proteins (CUX1, CUX2, and SATB1) is required for the survival of cancer cells that exhibit high ROS levels, this biochemical activity does not appear to be essential to non-transformed cells in normal physiological situations." (PMID 34204734, 2021). "Our findings are further supported by data from the pathology atlas of the human cancer transcriptome in combination with the Human Protein Atlas that reports CUX1 protein expression is mainly not consistent with CUX1 RNA expression data." (PMID 32180898, 2020). "Notwithstanding the effect of CUX1 in the absence of radiation, our results clearly established that CUX1 expression level impacts on the response of cancer cells to radiation." (PMID 28147323, 2017). "Importantly, OGG1 knockdown or inhibition, like CUX1 knockdown, sensitized DLD-1 cancer cells to radiation." (PMID 28147323, 2017). "Indeed, the present study strongly suggests that GLIS1 and CUX1 play an important role in the promotion of both the Wnt signaling and the EMT phenotype in many cancer cells." (PMID 25217618, 2014). "Moreover, the transcription factor CUX1, by targeting key subunits of the Wnt/β-Catenin pathway, showed a positive correlation with mRNA expression of Axin2, CTNNB1, and TCF4 in most normal and cancer tissues or cell lines." (PMID 34422906, 2021). "Consequently, clonogenic results expressed relative to that of non-irradiated cells indicate that CUX1 knockdown confers no or modest radiosensitivity to cancer cells with high ROS." (PMID 28147323, 2017). "Furthermore, 15 genes were expressed in the CUX1-19635798-MULTIPLE HUMAN CANCER CELL TYPES-HUMAN transcription factor binding site profile database, which contains 2406 expressed genes with transcription factor binding evidence in multiple human cancer cell types." (PMID 36768794, 2023). "Therefore,CUX1 activated by Snail-Cat L signaling may contribute to TNBCvia ER-α repression, and may be a viable target for TNBCusing natural products such as MSKE that targets cancer and not normalcells." (PMID 30964885, 2019).
infection (7 papers, 2009 to 2025). The state of being infected such as from the introduction of a foreign agent such as serum, vaccine, antigenic substance or organism. "A significant effect on CUX1 knockdown was achieved after infection with pLK.O1 lentivirus expressing shRNA-1." (PMID 37891174, 2023). "Forty-eight hours after infection, downregulation of CUX1 and decreased expression of p16INK4a were confirmed by both immunoblot and qPCR analysis." (PMID 37117763, 2022). "To test this notion, we examined the proliferation of IMR90 human primary lung fibroblast cells following infection with retroviruses expressing HRASG12V, p200 CUX1, or control virus." (PMID 24618719, 2014). "Whereas sgRNAs targeting known essential genes were depleted from both experimental groups as expected, the abundance of the majority of sgRNAs, including control sgRNAs, were not preferentially altered in CUX1−/− cells compared with wild-type after 21 days from sgRNA library infection." (PMID 33931647, 2021). "Interestingly, in cell lines that are not defective for CUX1, Lats1 expression was also stimulated following the infection of cells with a retrovirus expressing p110 or p75 CUX1." (PMID 19656388, 2009).
neurodevelopmental disorder (4 papers, 2017 to 2025). A behavioral and cognitive disorder with onset during the developmental period that involves impaired or aberrant development of intellectual, motor, or social functions. "In the present study, we describe 34 individuals with CUX1 variants showing haploinsufficiency and refine the phenotypic spectrum of the CUX1-related neurodevelopmental disorder (NDD), including 11 previously published individuals." (PMID 37644171, 2023). "In conclusion, we describe 34 individuals with potential causative variants in CUX1 and delineate the underlying neurodevelopmental disorder." (PMID 37644171, 2023). "Because CCP1 cKO mice showed increased cortical number of Cux1+ PNs at P21, our new mouse line might by a relevant model to explore the cellular and molecular mechanisms of ASD or other neurodevelopmental disorder characterized by abnormal cortical neurons numbers." (PMID 29474907, 2018).
cardiovascular disease (2 papers, 2021). "Among cardiovascular disease-relevant, differentially methylated genes in males, Atg5, Ank2, Cux1 and Lamp2 exhibited significant increases in gene expression." (PMID 33445541, 2021).
hematologic disease (1 paper, 2021). "Strikingly, all Cux1+/−;Flt3ITD mice developed lethal hematologic disease with a median survival of 28 weeks, while control (Con) and single-allele (Cux1+/− and Flt3ITD) groups remained healthy." (PMID 33931647, 2021).
hematologic neoplasms (1 paper, 2017). "CUX1, a haploinsufficient TF, is a new mediator that contributes to long-range interactions between enhancers and sites close to the TSS in hematologic neoplasms and solid tumors; 32-49% of CUX1 co-localizes with RNA Pol II, and 34-70% of CUX1 co-localizes with EP300, a transcriptional co-activator." (PMID 29149895, 2017).
psychiatric disorder (1 paper, 2021). A disorder characterized by behavioral and/or psychological abnormalities, often accompanied by physical symptoms.
CUX1 also shares sentences with these, for which no sentence is quoted: autism (3 papers); lung adenocarcinoma (3); Uterine leiomyoma (3); colon cancer (2); diabetes (2); hematological cancers (2); acute myocardial infarction (1); adenocarcinoma (1); adenosquamous carcinoma (1); Bardet-Biedl syndrome (1); benign tumor (1); chronic kidney disease (1); chronic myelomonocytic leukemia (1); chronic myeloproliferative disease (1); colorectal adenoma (1); congenital diaphragmatic hernia (1); Duane retraction syndrome (1); endometrial cancer (1); esophageal squamous cell carcinoma (1); gastric cancer (1); heart failure (1); hepatocellular carcinoma (1); hypertrophic cardiomyopathy (1); Insulin resistance (1); ischemic stroke (1); kidney disease (1); leukocytosis (1); lymphoma (1); major depressive disorder (1); mastitis (1).
A further 14 diseases each share a sentence with CUX1 in 1 paper.